KCND3 (potassium voltage-gated channel subfamily D member 3)
Diseases named in the same sentence as KCND3 in open-access papers (continued):
Sharing a sentence is not in itself a finding about the gene and the disease.
atrial fibrillation (16 papers, 2012 to 2025). A disorder characterized by an electrocardiographic finding of a supraventricular arrhythmia characterized by the replacement of consistent P waves by rapid oscillations or fibrillatory waves that vary in size, shape and timing and are accompanied by an irregular ventricular response. "Another study reported two teenage siblings having paroxysmal atrial fibrillation that is associated with a V392I mutation in the KCND3 gene confirmed by Sanger sequencing." (PMID 36883079, 2023). "SNPs near KCND3 have been associated with P-wave duration and ST-T wave amplitude, and with Atrial Fibrillation in the Japanese population." (PMID 30679814, 2019). "Previous studies have linked dysfunctional Ito arising from mutations to KCND3-encoded Kv4.3 and KCND2-encoded Kv4.2 to atrial fibrillation." (PMID 37122220, 2023). "Gain-of-function (GOF) mutations supported by enhanced channel trafficking have also been reported for KCNQ1 in both inherited atrial fibrillation and short QT syndrome as well as for KCND3 in atrial fibrillation (AF)." (PMID 34572065, 2021). "Previous investigations reported that the transient outward currents (Ito) decreased in the patients with atrial fibrillation and that down-regulation of KCND3/Kv4.3 expression contributed to the reduction of Ito currents, increasing the susceptibility for atrial tachycardia." (PMID 31912231, 2020). "In line with the observations from atrial fibrillation and heart failure, we also detected a down-regulation of KCND3/Kv4.3 expression and the decrease in Ito currents, which might be an important contributor to post-Fontan atrial arrhythmia." (PMID 31912231, 2020). "KCND3 mutation induced cardiocerebral channelopathy with early repolarization syndrome (ERS) and atrial fibrillation (AF)n as cardiac phenotype." (PMID 36883079, 2023).
Intellectual disability (9 papers, 2015 to 2024). "KCND3 has also been reported to play a role in potassium channel disorders, which are crucial for maintaining electrical activity and signaling in neurons and other cells, with mutations in KCND3 and related genes causing intellectual disability." (PMID 39595393, 2024).
cardiac hypertrophy (8 papers, 2014 to 2024). "Compared with NC group, the expression of cardiac hypertrophy related genes including NPPA, NPPB, and MHY7 in NC + Ang II group was significantly up-regulated, while KCND3 was down-regulated." (PMID 34248630, 2021). "Previous studies have confirmed that miR‐195 expression is increased in cardiac hypertrophy, and the bioinformatics website predicted by Targetscan software shows that miR‐195 can directly target CACNB1, KCNJ2 and KCND3 to regulate Cavβ1, Kir2.1 and Kv4.3 proteins expression." (PMID 32468736, 2020).
long QT syndrome (7 papers, 2011 to 2025). "Genetic analysis was done in 12 cases of long QT syndrome, and no mutation related to KCND3 was found." (PMID 36883079, 2023). "In humans, drug effects on hERG, SCN5A (Nav1.5), KCNQ1/MinK and KCND3/KChiP2 (Kv4.3) channels often lead to Long QT syndrome (LQTS) or Short QT syndrome (SQTS), including Torsade de Pointes (TdP) arrhythmias, fraught with ventricular fibrillation and ultimately death." (PMID 22039467, 2011).
Spinocerebellar ataxia type 19 (7 papers, 2015 to 2023). "It was shown that a mutation in KCND3 was associated with the autosomal dominant inherited neurodegenerative disorder, spinocerebellar ataxia types 19 and 22 (SCA19/22)." (PMID 33343629, 2020). "However, mutations within KCND3, which encodes the voltage-gated potassium channel α-subunit Kv4.3, have been found to cause spinocerebellar ataxia type 19/22 in humans." (PMID 31999692, 2020). "Worth mentioning is the fact that Kcnd3 mutations were associated with the neurodegenerative disorder spinocerebellar ataxia type 19, suggesting that MITF impact on Kcnd3 may also regulate neuronal function in the central and peripheral nervous system." (PMID 35665902, 2022). "Recently, we identified loss-of-function mutations in the KCND3 gene as the cause of spinocerebellar ataxia type 19/22 (SCA19/22), revealing a previously unknown role for the voltage-gated potassium channel, Kv4.3, in Purkinje cell survival." (PMID 25854634, 2015). "Spinocerebellar ataxia type 19 (SCA19), allelic with spinocerebellar ataxia type 22 (SCA22), is a rare syndrome caused by mutations in the KCND3 gene which encodes the potassium channel Kv4.3." (PMID 29527639, 2018).
channelopathies (6 papers, 2018 to 2025). "The locus in the KCND3 ion channel gene is an intuitive candidate and supports the theory that at least a proportion of ERS is a pure channelopathy." (PMID 31600170, 2019).
Cognitive impairment (5 papers, 2015 to 2023). Abnormal cognition is characterized by deficits in thinking, reasoning, or remembering. "Cognitive impairment and neurodevelopmental disorders such as developmental delay (DD), ID and learning disabilities are variably present in patients with KCND3 mutations." (PMID 32823520, 2020). "Moreover, KCND3 pathogenic variants may be responsible for a wider phenotypic spectrum than previously thought, including autosomal recessive early-onset sporadic cerebellar ataxia, childhood epileptic encephalopathy, Parkinsonism, and cognitive impairment." (PMID 33343629, 2020). "Neither cognitive impairment nor behavioural dysfunction were noticed in the large Chinese KCND3 kindred." (PMID 26189493, 2015).
early repolarization syndrome (5 papers, 2018 to 2025). "Possible mutations associated with early repolarization syndrome are mainly SCN5A or KCND3 mutations." (PMID 40926197, 2025). "Moreover, a missense variant in the C-terminus, p.R431C, was linked to episodic ataxia and a de novo duplication of KCND3 was reported to cause early repolarization syndrome." (PMID 32709127, 2020).
autosomal dominant cerebellar ataxia (2 papers, 2019 to 2020). A clinically and genetically heterogeneous group of neurodegenerative diseases characterized by a slowly progressive ataxia of gait, stance and limbs, dysarthria and/or oculomotor disorder, due to cerebellar degeneration in the absence of coexisting diseases. "Autosomal dominant cerebellar ataxia (SCA type 22) shows heterozygous mutations in the voltage-gated potassium channel Kv4.3-encording KCND3 gene." (PMID 31263403, 2019). "KCND3 is the causative gene of SCA 19/22, an autosomal dominant cerebellar ataxia mapped to chromosome 1p21-q23." (PMID 32823520, 2020).
diabetic kidney disease (2 papers, 2021 to 2024). Progressive kidney disorder caused by vascular damage to the glomerular capillaries, in patients with diabetes mellitus. "RNA sequencing analysis revealed that KCND3 was the only upregulated gene and a significant biomarker in diabetic kidney disease." (PMID 39072272, 2024).
dyslipidemia (2 papers, 2022 to 2023). "Other variants associated with CI2 were observed on KCND3, DIPK2B, and LIPC/ALDH1A2, which have already been identified in lipoprotein and dyslipidemia studies." (PMID 37372394, 2023).
peripheral nerve injury (2 papers, 2019). Injury to a peripheral nerve. "Upregulation of REST after peripheral nerve injury has been shown to correlate with the downregulation of some of its target genes in DRG, including Kcnd3,39Kcnq2,30Scn10a,38 and Oprm138,44; these genes are coding for Kv4.3, Kv7.2, Nav1.8 ion channels and μ-opioid receptors, respectively." (PMID 31206463, 2019).
spina bifida (2 papers, 2020 to 2025). A congenital neural tube defect in which vertebrae are not fully formed. "As a gene encoding potassium voltage-gated channel subfamily D member 3, KCND3 was predicted to be co-regulated by miR-142-3p and miR-765 in spina bifida." (PMID 33343629, 2020). "Based on our preliminary experimental validation results, KCND3 was upregulated in the spina bifida group, which supports that KCND3 may play a role in the development of spina bifida." (PMID 33343629, 2020). "Following the verification of qRT-PCR and KCND3 was upregulated in spina bifida." (PMID 33343629, 2020). "Following the verification of qRT-PCR and KCND3 was upregulated in the spina bifida." (PMID 33343629, 2020). "In this study, we identified a miRNA–mRNA regulatory network including four miRNAs and 39 mRNAs in spina bifida and implicate TSPAN6, YOD1, and KCND3, ubiquitylation pathways, and an antiviral immune response as modulators of neural tube malformations." (PMID 33343629, 2020). "PCP—Planar Cell Polarity; NTDs—Neural Tube Defects; SB—Spina Bifida; miRNA—microRNA; KCND3—Potassium Voltage-Gated Channel Subfamily D Member 3; VANGL2—Van Gogh-Like Protein 2Recent advances in miRNA profiling have provided valuable insights into the molecular mechanisms underlying SB." (PMID 40710310, 2025).
Strabismus (2 papers, 2015 to 2021). A misalignment of the eyes so that the visual axes deviate from bifoveal fixation. "Other unique phenotypic features in our case were strabismus, severe oral apraxia, and joint hyperlaxity, which are all supposedly part of the phenotype of this de novo KCND3 mutation." (PMID 26189493, 2015).
autism (1 paper, 2016). Persistent deficits in social interaction and communication and interaction as well as a markedly restricted repertoire of activity and interest as well as repetitive patterns of behavior. "We analyzed the Simons Simplex Collection of 2508 parent-offspring autism trios using VARPRISM, replicating 44 genes previously implicated in autism susceptibility and identifying 20 additional candidate genes, including MYO1E, KCND3, PDCD1, DLX3, and TSPAN4 (false discovery rate < 0.3)." (PMID 27562213, 2016).
conduction disorders (1 paper, 2021). "Similar to our differential gene expression analysis, we focused on alternative splicing events affecting genes involved in regulation of cardiac ion transport and previously implicated in conduction disorders — Scn5a, Kcnd3, Kcnip2, Ryr2, and Camk2d." (PMID 33497365, 2021).
Dystonia (1 paper, 2020). An abnormally increased muscular tone that causes fixed abnormal postures. "In summary, we reported a new patient with KCND3 mutation with neurodevelopmental disorder and prominent dystonia, with a clinical course paradigmatic of the early onset forms." (PMID 32823520, 2020).
glioblastoma (1 paper, 2025). The most malignant astrocytic tumor (WHO grade IV). "Glioblastoma studies included E5 (KCNJ10, KCNN3), E21 (KCNAB2), E26 (KCNE2, KCNJ13), E27 (KCNE4, KCNMB2-AS1), E31 (KCNJ10), E50 (KCND3), and E51 (KCNIP1, KCNJ16, KCNN2)." (PMID 40867621, 2025).
hidradenitis suppurativa (1 paper, 2025). A chronic suppurative and cicatricial disease of the apocrine glands occurring chiefly in the axillae in women and in the groin and anal regions in men. "Potassium channels: Pain perception in hidradenitis suppurativa may be significantly influenced by the dysregulation of potassium channels, including genes such as KCNMA1, KCNQ5, KCNB2, KCND2, KCND3, and KCNAB3, all of which were identified in this study." (PMID 39940809, 2025).
learning disabilities (1 paper, 2020). "The strikingly high percentage of DD, ID, and learning disabilities in KCND3 early-onset patients remarks this concept." (PMID 32823520, 2020).
lung carcinoma (1 paper, 2023). "So far, there have been no reports on other three down regulated mRNAs (KCND3, SCN1A and CYB561D1) in lung cancer targeted by miRNAs." (PMID 37185598, 2023).
melanoma (1 paper, 2020). A malignant, usually aggressive tumor composed of atypical, neoplastic melanocytes. "Analysis of two MITF ChIPseq datasets showed that MITF binds to intronic regions of KCND3 in 501mel melanoma cells." (PMID 32193365, 2020).
occupational asthma (1 paper, 2017). Asthma attacks caused, triggered, or exacerbated by OCCUPATIONAL EXPOSURE. "Of them, rs269094 was an expression quantitative trait locus (eQTL) for KCND3, previously shown to be associated with occupational asthma." (PMID 28139761, 2017).
polyneuropathy (1 paper, 2018). A disease or disorder affecting more than one nerve. "Differently to the described Japanese SCA19/22 patient harboring the T377M mutation in KCND3, we found polyneuropathy in two patients from the Swedish family who were also affected by T2DM." (PMID 29527639, 2018).
RSV bronchiolitis (1 paper, 2018). "Only one human GWA study has been done for RSV bronchiolitis that found several suggestive associations, one of which was also an expression QTL in KCND3 (potassium voltage-gated channel subfamily D member 3)." (PMID 29353387, 2018).
cancer (5 papers, 2011 to 2023). A tumor composed of atypical neoplastic, often pleomorphic cells that invade other tissues. "The potassium voltage‐gated channel subfamily D (KCND, also known as Kv4) consists of three members, including KCND1 (Kv4.1), KCND2 (Kv4.2), and KCND3 (Kv4.3), which have been widely documented to be responsible for the initiation and advancement of cancers." (PMID 37347147, 2023). "The methylation levels of CpG islands of KCND3 were higher in cancer secretion groups, while the methylation levels of KCNQ1 were lower than those in control and medium groups." (PMID 35265687, 2022). "The protein levels of SCN5A and KCND3 decreased and SCN10A and KCNQ1 increased, similar to the levels in AGS and SW480 cancer cell media treated cells." (PMID 35265687, 2022). "Furthermore, after using 3-Methyladenine (3-MA), an inhibitor of PI3K, the increased levels of phosphorylated PI3K and Akt were decreased, and DNMT3A, DNMT3B, KCND3, and KCNQ1 levels were also rescued compared with AGS and SW480 cancer cell media treated cardiomyocytes." (PMID 35265687, 2022).
cardiac disease (5 papers, 2020 to 2024). "The interaction between SNPs in KCND3 and LOC107984002 on 9-trans 12-trans octadecanoic acid may imply an association between omega-6 trans fatty acid, body fat deposition, and cardiac disease." (PMID 32915819, 2020).
neurological disorders (5 papers, 2016 to 2025). "To better define the phenotypic spectrum and course of KCND3-related neurological disorder, we review the clinical presentation and evolution in 68 reported cases." (PMID 32823520, 2020).
movement disorder (3 papers, 2020 to 2024). Neurological conditions resulting in abnormal voluntary or involuntary movement, which may impact the speed, fluency, quality and ease of movement. "After analysis of the exome data, only the pathogenic variant c.455G>A (p.D152G) in KCND3 can be linked to the observed ataxic movement disorder." (PMID 39180521, 2024). "Parkinsonian features, including rigidity or bradykinesia, were the most frequent movement disorder in KCND3 deficient patients, occurring in 9 out of 53 late-onset patients and in 3 out of 15 early-onset patients." (PMID 32823520, 2020). "Movement disorders in KCND3 patients are heterogenous and their prevalence is relatively high." (PMID 32823520, 2020).
metabolic disorders (2 papers, 2022 to 2023). "All metabolic disorders described in this group, except for DHPR deficiency, had a neurodegenerative course and 5/16 were associated to brand new genes or genes described in the last decade (e.g., WARS2, KCND3, DHDDS, HIBCH, WDR45)." (PMID 35795805, 2022). "In Group B 10/16 patients had a metabolic disorder (3/9 with Menkes disease), 3/16 a sodium or potassium channelopathy (SCN1A, KCNQ2, KCND3), 2/16 Rett syndrome, and 1/16 a synaptopathy." (PMID 35795805, 2022).
KCND3 also shares sentences with these, for which no sentence is quoted: cerebellar ataxia (11 papers); heart failure (10); cardiac arrhythmia (8); developmental delay (4); Parkinsonism (4); ventricular fibrillation (4); asthma (3); diabetes (3); neuropathic pain (3); Paroxysmal atrial fibrillation (3); spinocerebellar ataxia type 13 (3); sudden infant death syndrome (3); Ventricular arrhythmia (3); attention deficit-hyperactivity disorder (2); breast carcinoma (2); epileptic encephalopathies (2); episodic ataxia (2); glioma (2); injury (2); Obesity (2); tumor (2); adenocarcinoma (1); alcohol dependence (1); Alzheimer disease (1); amyotrophic lateral sclerosis (1); Anxiety (1); anxiety disorder (1); aortic coarctation (1); atrial tachycardia (1); Benign familial neonatal seizures (1).
A further 56 diseases each share a sentence with KCND3 in 1 paper.